PPM1D (protein phosphatase, Mg2+/Mn2+ dependent 1D)
Diseases named in the same sentence as PPM1D in open-access papers (continued):
Sharing a sentence is not in itself a finding about the gene and the disease.
cancer (continued). "Several cancer-associated genes have been identified on chromosome 17q, including PPM1D, EME1, BRCA1, ERBB2, NF1, RAD51C, BRIP1 and BIRC5." (PMID 34885154, 2021). "Although its loss impairs recovery from the G2 checkpoint and promotes induction of senescence, amplification of the PPM1D locus or gain-of-function truncating mutations of PPM1D occur in various cancers." (PMID 32927737, 2020). "We concluded that cancer cells carrying truncating mutations in the PPM1D gene are resistant to 5-FU treatment, whereas inhibition of PPM1D can restore the sensitivity to 5-FU." (PMID 31659152, 2019). "These gain-of-function PPM1D mutations are present in various human cancers but their role in tumorigenesis remains unresolved." (PMID 31659152, 2019). "In this study, we investigated the prevalence and characteristics of the truncating PPM1D mutation among patients with cancer by using NGS hereditary cancer panel testing." (PMID 31242196, 2019). "Because PPM1D also dephosphorylates and inactivates other proteins working in the DNA damage repair system, the truncating mutations of PPM1D are assumed to have a role in carcinogenesis in various types of cancers." (PMID 31242196, 2019). "Here we generated a mouse model mimicking the truncating mutation in PPM1D identified in human cancers." (PMID 31659152, 2019). "Other recurrent mutation targets that have been implicated in different types of cancers included PPM1D and GON4L." (PMID 27224912, 2016). "PPM1D (protein phosphatase, Mg2+/Mn2+ dependent, 1D), the gene encoding Wip1, is aberrantly amplified in different types of human primary cancers." (PMID 23256570, 2012). "PPM1D (protein phosphatase Mg2+/Mn2+-dependent 1D) is a master negative regulator of the response; gain-of-function mutations and amplifications of PPM1D are found across several human cancers making it a relevant pharmacological target." (PMID 38896450, 2024). "We speculate that other interventions that induce DNA damage may be required to unmask these dependencies in cancer cells that harbor other alterations beyond PPM1D mutations." (PMID 35105861, 2022). "The distribution of mutations of PPM1D is very similar across CH and cancer cases." (PMID 35871184, 2022). "The spectrum of cancers associated with PPM1D mutations is distinct in children compared to adults." (PMID 35105861, 2022).
cancer (continued). "Activating mutations and amplification of PPM1D are found across numerous cancer types." (PMID 35773251, 2022). "PPM1D amplification or gain-of-function mutations have been reported in different types of cancer." (PMID 34091011, 2021). "Finally, PPM1D mutation is also a common genetic lesion associated with clonal hematopoiesis during aging and cancer." (PMID 34091011, 2021). "We hypothesize that some of the PPM1D truncating mutations occur randomly in a fraction of colon stem cells, providing a selective advantage compared to healthy stem cells and potentially contributing to cancer development." (PMID 31659152, 2019). "A recent report presented the synergistic effect of inhibiting both MDM2 and PPM1D, showing that dual inhibition leads to a more pronounced apoptotic response in cancer cells." (PMID 40227763, 2025). "Given the oncogenic role of PPM1D, PPM1D inhibitors have gained attention as potential therapeutic agents for malignant tumors." (PMID 40931354, 2025). "Based on these findings, PPM1D inhibitors have been proposed as a potential therapeutic agent for malignant tumors." (PMID 40931354, 2025). "Despite these concerns, our findings provide a compelling rationale for continued exploration of proteasome and PPM1D co-inhibition as a novel approach in cancer therapy." (PMID 40931354, 2025). "miR-205-3p, a predicted repressor of PPM1D, demonstrated a subtype-dependent pattern—upregulated in luminal cancers but strongly suppressed in TNBC." (PMID 41465262, 2025). "Based on the commonly observed amplification of the PPM1D locus in human cancers as well as the phenotypes of PPM1D-/- mice that are resistant to tumour development, PPM1D has been proposed to act as an oncogene." (PMID 39237765, 2024). "It should be stressed, that inhibition of PPM1D alone doesn’t influence cancer cell growth, whereas a combination PPM1D inhibitor with chemotherapeutic drugs or radiation significantly enhances the cytostatic effect of DNA damage agents." (PMID 39702569, 2024). "While there is ample evidence that PPM1D is an oncogenic driver in many types of cancers, the clinical importance of targeting pre-malignant PPM1D-associated clonal expansion in the hematopoietic system is not clear." (PMID 38896450, 2024). "As a specific example, we consider the cancer drug target PPM1D/Wip1 phosphatase, a protein that lacks crystal structures." (PMID 37143823, 2023).
cancer (continued). "Our data link PPM1D gain-of-function mutations to the clonal expansion of HSCs, inform human genetic observations, and support the therapeutic targeting of PPM1D in cancer." (PMID 37595362, 2023). "The improvement of the pharmacokinetic properties of PPM1D inhibitors will likely lead to clinical trials on PPM1D inhibition in cancer." (PMID 36060052, 2022). "Among the 15 canonical genes associated with CH, our cancer patients had mutations in CHEK2, DNMT3A, ASXL1, PPM1D, and TET2 only." (PMID 35428225, 2022). "To demonstrate its applicability, we applied TC-hunter to four transgenic mice samples harboring the human PPM1D gene, a model used in the study of malignant tumor development." (PMID 35184734, 2022). "CCT007093 selectively and potently inhibits the activity of PPM1D, which overexpress on various cancers via activating p38 kinase activity." (PMID 35300596, 2022). "Consistent with the genetic data, PPM1D-dependent cancer cells also tended to be sensitive to pharmacologic inhibition of MDM2 using the MDM2 inhibitor Nutlin-3 (Pearson 0.38, P < 10−21)." (PMID 35105861, 2022). "Our finding that PPM1D is necessary for PPM1D-mutant DMGs extended to other PPM1D-expressing cancers." (PMID 35105861, 2022). "Owing to the function of PPM1D as an oncogene and the relatively mild phenotype of PPM1D depletion in adult mice, PPM1D inhibitors are being evaluated as anti-cancer drugs." (PMID 36060052, 2022). "Taken together, these findings confirm PPM1D expression to be necessary for the proliferation of PPM1D-mutant cancer cells, nominating it as a potential therapeutic target across multiple lineages." (PMID 35105861, 2022). "Overall, PPM1D, by regulating genome integrity, could play a significant role in ischemia-reperfusion injury, postinfarction remodeling, arrhythmogenic cardiomyopathy, cardiac complication associated with cancer therapy, and aging related chronic heart failure." (PMID 34091011, 2021). "This study illustrated that mRNA expression of PPM1D were correlated with several human cancer prognosis." (PMID 34470916, 2021). "The GEPIA database gene expression analysis revealed that higher PPM1D expression related with worse prognosis in cancers including HCC, BLCA, CESC, MESO and UVM." (PMID 34470916, 2021). "In concordance, PPM1D mutations, amplifications, gene fusions, and WIP1 overexpression have been observed in various cancers." (PMID 34771656, 2021). "We established a transgenic mouse model overexpressing PPM1D and showed that these mice developed a wide variety of cancers." (PMID 34771656, 2021). "The comparatively high levels of PPM1D in HCC and other cancers imply a high risk for tumor relapse after treatment." (PMID 34470916, 2021).
cancer (continued). "Overexpression of PPM1D promotes the growth and treatment resistance of pediatric and adult cancers." (PMID 34885154, 2021). "Amplification of the chromosomal locus 17q23.2 carrying the PPM1D is common in various cancer types and results in overexpression of enzymatically active PPM1D." (PMID 32927737, 2020). "Cancer cell lines (including U2OS and HCT116 cells) carrying heterozygous truncating mutations in PPM1D show G1 checkpoint override upon exposure to the mild level of IR." (PMID 32927737, 2020). "Next, we aimed to determine the impact of truncated PPM1D in the tissue context of and to evaluate its potential role in cancer growth." (PMID 31659152, 2019). "In parallel, we analyzed publicly available patient-derived cancer gene expression data from cBioPortal33,34 across tumor subtypes in which PPM1D is often found amplified, including brain, breast, and ovary." (PMID 31439867, 2019). "Since its discovery over 20 years ago, PPM1D has become a well-established oncogene, found amplified or over-expressed in a diverse range of cancers, including breast, ovarian, gastrointestinal, and brain cancers." (PMID 31439867, 2019). "Care must be taken when analyzing and interpreting hereditary cancer genes known to be mutated in a mosaic pattern, such as APC and PPM1D." (PMID 31269945, 2019). "Truncating mutations in the PPM1D gene that lead to Wip1 gain-of-function have been reported in HCT116 and U2OS cell lines as well as cancer patients." (PMID 30254262, 2018). "Based on data from PPM1D knockout mice and also from RNAi-mediated depletion of WIP1 in cancer cell lines, WIP1 was proposed as potential pharmacological target." (PMID 28439615, 2017). "PPM1D overexpression or amplification has been reported in various cancers, including lung, breast, kidney, and ovarian cancers." (PMID 27626308, 2016). "Determining the signal transduction pathways in cancer cells in which PPM1D participates is therefore a necessary step in the development of targeted therapy." (PMID 27619510, 2016). "PPM1D inhibitor has been proposed as therapeutic approaches for some cancers." (PMID 39702569, 2024).
cancer (continued). "Ongoing efforts are underway to develop SOD1 inhibitors for the treatment of cancer and ALS, and it is conceivable these may be useful in the context of PPM1D mutation." (PMID 38896450, 2024). "Given the prevalence of PPM1D aberrations in cancer, PPM1D is an attractive therapeutic target." (PMID 38896450, 2024). "GSK2830371 is a potent and selective allosteric WIP1/PPM1D inhibitor used in cancer therapy." (PMID 37373360, 2023). "It is tempting to speculate that besides the established role of the overexpressed PPM1D in overriding the cell cycle checkpoint, the increased activity of PPM1D could promote genome instability in cancer cells by interfering with the telomere functions." (PMID 36651296, 2023). "As truncating PPM1D mutations frequently occur in therapy-induced AML and MDS, we decided to explore the connection between truncating PPM1D mutations, exposure to genotoxic agents, and cancer development." (PMID 37709843, 2023). "Several of the cancer-related genes we identified, including PIK3CA, KRAS, GNAS, and PPM1D, could also have haematological mutations." (PMID 37175518, 2023). "Ppm1d hyperactivity also seems to restrict the infiltration of tumors by antitumor neutrophils, suggesting that Ppm1d inhibition may enhance the effects of cancer immunotherapy." (PMID 36060052, 2022). "Only in N0, DNA (excision-) repair (involved genes: CDKN1A, PPM1D, and DDB2) was predicted to be a downstream function, while molecular networks in N2+ were associated with cancer, as well as injury and abnormalities (among others, downregulation of MSH6, CCNE2, and CHUK)." (PMID 36068491, 2022). "Our findings suggest that PPM1D might be an underlying prognostic marker for HCC, that could be taken to determine the rate of immune cells infiltration in cancer tissue." (PMID 34470916, 2021). "Although these findings indicate differences in the level of tumor infiltration by the immune cell, the mRNA expression of PPM1D and prognosis in various tumors, the results generally imply that mRNA expression of PPM1D modulates the infiltration of the immune cells to cancer tissues." (PMID 34470916, 2021). "Our results suggest that PPM1D can act as an oncogenic driver by inducing genomic instability, impaired growth arrest, and apoptotic escape that can result in neoplastic transformation and malignant tumor development." (PMID 34771656, 2021). "Several human cancers exhibit PPM1D gene amplification and/or overexpression of the WIP1 protein." (PMID 34771656, 2021).